OPCML (opioid binding protein/cell adhesion molecule like)
Diseases named in the same sentence as OPCML in open-access papers (continued):
Sharing a sentence is not in itself a finding about the gene and the disease.
gastric cancer (7 papers, 2011 to 2025). A primary or metastatic malignant neoplasm involving the stomach. "The downregulation of OPCML in colorectal and gastric cancers was significantly associated with promoter methylation at a region from − 125 to + 4 bp of the transcription start site (TSS)." (PMID 30832707, 2019). "OPCML expression exhibited a significant association with overall survival time of gastric cancer patients (P = 0.031)." (PMID 28407749, 2017). "We subsequently analyzed the association between OPCML expression and clinicopathological characteristics of gastric cancer patients." (PMID 28407749, 2017). "We also explored the biological functions of OPCML in tumor progression, and the molecular mechanisms underlying its behavior in gastric cancer." (PMID 28407749, 2017). "Moreover, we evaluated the association of OPCML expression and clinicopathological characteristics and prognosis in gastric cancer." (PMID 28407749, 2017). "The findings in this study suggested that AKT/GSK3β signaling pathway might be implicated in the tumor-suppressing function of OPCML in gastric cancer." (PMID 28407749, 2017). "Silencing of OPCML has been implicated in metastasis of gastric cancer." (PMID 21731750, 2011). "Low expression of OPCML due to promoter hypermethylation promotes cell proliferation and short survival in gastric cancer." (PMID 30832707, 2019). "Next, our study explored the effect of OPCML on the growth of gastric cancer cells in vitro and in vivo." (PMID 28407749, 2017). "Using MSP, we determined the promoter methylation of OPCML in these seven gastric cancer cell lines." (PMID 28407749, 2017). "We first used immunohistochemical assay to directly compare the expression of OPCML in gastric cancer tissues and their adjacent normal tissues in 30 gastric cancer patients." (PMID 28407749, 2017). "This study revealed that AKT and its downstream target GSK3β were constitutively phosphorylated in the two gastric cancer cell lines and their phosphorylation levels were markedly suppressed by ectopic expression of OPCML." (PMID 28407749, 2017). "In the current study, we showed that OPCML was expressed in the normal stomach while markedly down-regulated or lost in gastric cancer." (PMID 28407749, 2017). "Next, we assessed the differential expression of OPCML in tumor samples from 133 patients with gastric cancer." (PMID 28407749, 2017). "The results showed that expressions of both OPCML mRNA and protein were markedly down-regulated or lost in all seven gastric cancer cell lines, while it is readily detectable in the normal stomach tissues." (PMID 28407749, 2017). "Further multivariate regression analysis revealed that reduced OPCML expression is an independent predictor for poor outcome of gastric cancer patients." (PMID 28407749, 2017). "The results revealed that the expression of OPCML was reduced in tumor samples from 96/133(72.2%) patients with gastric cancer and was completely lost in tumor tissues from 45/133 (33.8%) gastric cancers." (PMID 28407749, 2017). "Taken together, these data thus suggest the role of OPCML as a candidate tumor suppressor in gastric cancer." (PMID 28407749, 2017). "We next assessed the correlation between OPCML expression and clinical outcome of patients with gastric cancer." (PMID 28407749, 2017). "The results point to the independent prognostic significance of reduced OPCML expression in gastric cancer (HR = 2.34, 1.38–3.97; P = 0.002)." (PMID 28407749, 2017). "In the first place, we performed immunohistochemistry to assess OPCML expression in 30 paired gastric cancer tissues and their adjacent normal gastric tissues." (PMID 28407749, 2017). "Low expression of OPCML protein was exhibited in tumor tissues from 96/133 (72.2%) patients with gastric cancer." (PMID 28407749, 2017). "The constitutive phosphorylation of GSK3β was present in gastric cancer cells and its phosphorylation level was shown to be markedly reduced by ectopic OPCML expression." (PMID 28407749, 2017).
gastric cancer (continued). "OPCML protein was shown to be significantly reduced in gastric cancer tissues, while readily expressed in adjacent normal stomach tissues." (PMID 28407749, 2017). "We assessed expression and biological behavior of OPCML in gastric cancer." (PMID 28407749, 2017). "OPCML had a tumor-suppressing activity possibly via AKT/GSK3β signaling in gastric cancer." (PMID 28407749, 2017). "In addition, our study showed that OPCML protein and mRNA were significantly decreased or lost in all 7 gastric cancer cell lines, as compared to the normal stomach tissues." (PMID 28407749, 2017). "Moreover, OPCML expression was found to be completely lost in samples from 45/133 (33.8%) gastric cancers." (PMID 28407749, 2017). "To assess whether OPCML expression is an independent prognostic factor for gastric cancer, we conducted a Cox multivariate regression analysis including age, tumor stage, nodal status, state of metastasis, grading and OPCML expression." (PMID 28407749, 2017). "Notably, the decrease of OPCML expression was significantly more frequent in the advanced stages of gastric cancer, in comparison to the early stages." (PMID 28407749, 2017). "Besides, the suppressive effect of OPCML on the growth of gastric cancer cells was confirmed in the subsequent experiments on nude mice." (PMID 28407749, 2017). "Furthermore, the results revealed that OPCML was an independent prognostic factor for overall survival in gastric cancer (p = 0.002)." (PMID 28407749, 2017). "Interestingly, gastric cancer patients with decreased OPCML expression possessed a significantly shorter survival as compared to cancers with preserved OPCML expression." (PMID 28407749, 2017). "We detected the expression of OPCML in seven gastric cancer cell lines." (PMID 28407749, 2017). "The results suggest that decreased OPCML expression might predict poor prognosis and promote disease progression in gastric cancer." (PMID 28407749, 2017). "Taken together, these data revealed that reduction of OPCML expression might have the important clinical significance in the progression of gastric cancer." (PMID 28407749, 2017). "In conclusion, our study revealed that reduced expression of OPCML might have a significant correlation with unfavorable tumor stage and differentiation, and might independently predict poor prognosis of patients with gastric cancer." (PMID 28407749, 2017). "We further examined whether OPCML inhibited the growth of gastric cancer cells in vivo." (PMID 28407749, 2017). "Down-regulated OPCML expression might serve as an independent predictor for unfavorable prognosis of patients, and the biological behavior supports its role as a tumor suppressor in gastric cancer." (PMID 28407749, 2017). "However,the clinical implications and biological functions of OPCML in the progression of gastric cancer remain unknown." (PMID 28407749, 2017). "The results showed that AKT was constitutively activated in the two gastric cancer cell lines, and the phosphorylation level of AKT was significantly decreased by ectopic expression of OPCML." (PMID 28407749, 2017). "To understand the function of OPCML gene in gastric cancer, we assessed the effect of ectopic expression of OPCML on the growth of SGC-7901 and BGC-823 cells in which OPCML gene was silenced." (PMID 28407749, 2017). "OPCML belongs to the IgLON family of Ig domain–containing GPI-anchored cell adhesion molecules and was recently found to be involved in carcinogenesis, while its role in gastric cancer remains unclear." (PMID 28407749, 2017).
prostate carcinoma (6 papers, 2008 to 2023). A carcinoma that arises from epithelial cells of the prostate gland. "Our present study further verifies that OPCML can function as a broad TSG and is frequently inactivated epigenetically in multiple carcinomas and lymphomas, including NPC, esophageal, lung, gastric, hepatocellular, colorectal, breast, cervical and prostate carcinomas." (PMID 18714356, 2008).
lung carcinoma (5 papers, 2007 to 2021). "We recently reported OPCML as highly methylated in lung adenocarcinoma, indicating that it is a potential AD/SQ lung cancer biomarker." (PMID 18616821, 2008). "The ability of the top four candidates, CDKN2A EX2, CDX2, HOXA1 and OPCML (all p < 1 × 10-9), to individually identify lung cancer samples was next evaluated." (PMID 17967182, 2007). "OPCML, TNFRSF25 and TCF21 have been previously reported to be hypermethylated in lung cancer and based on their function, methylation-induced silencing could favor tumor growth." (PMID 18616821, 2008). "Given that opioids have demonstrated growth inhibitory and pro-apoptotic effects in lung cancer cells, it is perhaps not surprising that the OPCML promoter CpG island might be a target for DNA methylation in lung cancer." (PMID 17967182, 2007).
breast carcinoma (4 papers, 2007 to 2025). "Preclinical studies in ovarian and breast cancer models have demonstrated that treatment with recombinant OPCML reduces tumor growth and enhances sensitivity to small molecule RTK inhibition." (PMID 40699804, 2025). "The findings show that luteolin slows breast cancer cell proliferation via lowering methylation and increasing OPCML gene expression." (PMID 35327559, 2022). "Previous study in ovarian and breast cancers showed that OPCML can disrupt EGFR-HER2 heterodimerization by binding to HER2 and inhibiting downstream pathway." (PMID 30832707, 2019).
esophageal cancer (4 papers, 2008 to 2025). A primary or metastatic malignant neoplasm involving the esophagus. "The gene OPCML has a known role as a tumour suppressor gene and is downregulated in breast and oesophageal cancers." (PMID 35774118, 2022). "Another example of GPI-anchored proteins playing a role in cancer development is the gene OPCML, which has a known role as a cancer suppressor gene and was found to be downregulated in breast and oesophageal cancers." (PMID 35774118, 2022). "In the context of esophageal cancer, OPCML’s downregulation in Grade 3 tumors may implicate its regulatory role in the Wnt/β-catenin signalling pathway, potentially contributing to the development and progression of higher-grade tumors." (PMID 39236081, 2024). "The high incidence of epigenetic inactivation of OPCML in NPC and esophageal carcinoma, both prevalent in our locality, indicates that OPCML methylation could be an epigenetic biomarker for the molecular diagnosis of these tumors." (PMID 18714356, 2008).
autism (3 papers, 2022 to 2025). Persistent deficits in social interaction and communication and interaction as well as a markedly restricted repertoire of activity and interest as well as repetitive patterns of behavior. "OPCML has been identified as a risk gene for PTSD and NTM is a risk gene for autism." (PMID 40301990, 2025).
colorectal cancer (3 papers, 2016 to 2025). A primary or metastatic malignant neoplasm that affects the colon or rectum. "Similarly, expression of WT OPCML in the colorectal cancer cell line HCT116 decreased the phosphorylation of ERK1/2 but the OPCML mutants could not." (PMID 31316070, 2019).
glioma (3 papers, 2008 to 2025). A benign or malignant brain and spinal cord tumor that arises from glial cells (astrocytes, oligodendrocytes, ependymal cells). "What is new here is the GBM-specific link: we show that OPCML loss is associated with elevated p-AKT/p-mTOR in glioma cells and that PI3K blockade normalizes these readouts, potentially linking a neural adhesion molecule with a canonical survival pathway in this disease context." (PMID 41561740, 2025). "Because the IDH status is a key disease determinant, we examined OPCML in that context: OPCML was generally lower in the IDH-wild-type GBM than in the IDH-mutant gliomas." (PMID 41561740, 2025). "Among these, CDH13, TIAM1 and PCDH17 were up- and FLRT1 and OPCML down-regulated, thus indicating that the invasion capacity of glioma cells can be altered by cisplatin treatment." (PMID 21637621, 2010). "OPCML is significantly down-regulated in brain tumors, including gliomas." (PMID 21637621, 2010).
lung adenocarcinoma (3 papers, 2007 to 2021). A carcinoma that arises from the lung and is characterized by the presence of malignant glandular epithelial cells. "To our knowledge, CDKN2A EX2, CDX2, HOXA1 and OPCML constitute the strongest lung adenocarcinoma DNA methylation markers identified to date, and we are working on further evaluations of their potential with great anticipation." (PMID 17967182, 2007). "The four most highly ranked loci, CDKN2A EX2, CDX2, HOXA1 and OPCML, which show significant DNA methylation even in stage IA tumor samples, merit further investigation as some of the most promising lung adenocarcinoma markers identified to date." (PMID 17967182, 2007). "Thus, we suggest that CDKN2A EX2, CDX2, HOXA1 and OPCML are the top candidates from the 28 tested, and should be validated as DNA methylation markers for lung adenocarcinoma." (PMID 17967182, 2007). "The expression levels of LSAMP and NTM in tumor tissues were lower than that in normal tissue samples of lung adenocarcinoma (LUAD); however, the levels of OPCML were relatively inconsistent." (PMID 34202934, 2021). "Based on the results of our analyses, four loci that are very strong candidates for a DNA methylation panel aimed at early lung adenocarcinoma detection have been identified: CDKN2A EX2, CDX2, HOXA1 and OPCML." (PMID 17967182, 2007). "Although the OPCML locus was not studied in detail in the Bibikova study, the observed methylation supports the idea that OPCML is a strong candidate marker in lung adenocarcinoma." (PMID 17967182, 2007). "Using the current tissue collection and 5-fold cross validation, the four most significant loci (CDKN2A EX2, CDX2, HOXA1 and OPCML) individually distinguish lung adenocarcinoma from non-cancer lung with a sensitivity of 67–86% and specificity of 74–82%." (PMID 17967182, 2007).
Alzheimer disease (2 papers, 2017 to 2023). A progressive, neurodegenerative disease characterized by loss of function and death of nerve cells in several areas of the brain leading to loss of cognitive function such as memory and language. "Within neurodegenerative diseases, OPCML has been implicated in Alzheimer’s disease in a GWAS carried out in patients affected by the late-onset form." (PMID 37895235, 2023). "In addition, reduced OPCML glycosylation in Alzheimer’s disease brains, together with other CAMs, was interpreted as a driver of altered cell adhesion and synaptic function in the disorder." (PMID 37895235, 2023).
brain tumors (2 papers, 2010 to 2025). "Historically, OPCML has been reported as downregulated in brain tumors, including GBM, and as epigenetically silenced across multiple cancer types." (PMID 41561740, 2025).
chronic cholecystitis (2 papers, 2019 to 2022). "The high methylation level of OPCML observed in sera of some cases in other biliary diseases such as chronic cholecystitis (7/19) and papillary adenoma (5/9) may reflect an increase risk in developing CCA in the future in which clinical follow up of these patients should be concerned." (PMID 30832707, 2019).
colon cancer (2 papers, 2016 to 2017). "LOH and immunohistochemistry supported the role of DGKI, EPCAM, and OPCML in clinical colon cancer specimens." (PMID 27047543, 2016).
hepatocellular carcinoma (2 papers, 2011 to 2015). A malignant tumor that arises from hepatocytes. "The expression of genes encoding proteins known to be associated with the cell cycle (E2F1), adhesion and proteolysis (OPCML) and hepatocellular carcinoma (FZD7, IGFBP1 and LEF1) was elevated 3- to 9-fold." (PMID 26442469, 2015).
Autoimmunity (1 paper, 2019). The occurrence of an immune reaction against the organism's own cells or tissues. "Several genes, such as TREX1, FLI1, EVI5, IL1RAPL1, are known for their role in autoimmunity, with EVI5 being an established MS risk gene, whereas others, such as CBFB, OPCML and KMT2A, are involved in lymphoproliferative disorders (OMIM)." (PMID 30541027, 2019).
coronary artery disease (1 paper, 2021). "Furthermore, NEGR1 has been found to control endothelial integrity in human brain microvessels; LSAMP has been shown to be implicated in the coronary artery disease and both LSAMP and OPCML have been shown to be implicated in the epithelial-mesenchymal transition." (PMID 34203377, 2021).
ependymoma (1 paper, 2023). A WHO grade II, slow growing tumor of children and young adults, usually located intraventricularly. "However, normal glial cells and glia-like tumor cells have their specific lineage-associated genes, such as FABP7 and MSX1 in normal ASCs, OLIG2 and OPCML in normal OPCs and OLs, FRMD5 in ASC-like ependymomas and GLUL in OPC/OL-like ependymomas." (PMID 37095395, 2023).
esophageal adenocarcinoma (1 paper, 2018). A malignant tumor with glandular differentiation arising predominantly from Barrett mucosa in the lower third of the esophagus. "We examined methylation levels in the first exon of OPCML in two patient cohorts within the esophageal adenocarcinoma and gastric adenocarcinoma cascades and in a range of cell-lines using a custom PyroMark CpG assay." (PMID 30555700, 2018).
glioblastoma (1 paper, 2025). The most malignant astrocytic tumor (WHO grade IV). "A high OPCML expression was linked to longer overall survival in TCGA glioblastoma, and multivariable Cox modeling confirmed the gene as an independent protective factor." (PMID 41561740, 2025). "OPCML (opioid-binding protein/cell adhesion molecule-like), a glycosylphosphatidylinositol (GPI)-anchored IgLON adhesion molecule with brain-enriched expression, has tumor-suppressive roles in several epithelial cancers; however, its role in glioblastoma (GBM) biology is unclear." (PMID 41561740, 2025).
keloid (1 paper, 2024). An irregularly shaped, elevated mark on the skin caused by deposits of excessive amounts of collagen during wound healing. "OPCML exhibited the greatest upregulation among those genes in keloids." (PMID 38622256, 2024). "Of those, six genes (i.e., OPCML, S100A7, S100 calcium binding protein A8 [S100A8], KANK4, PTPRD, tenascin XB [TNXB]) were significantly differentially expressed between keloid and immature scar samples." (PMID 38622256, 2024). "We performed immunohistochemical analysis of OPCML in keloids and immature scars, and found that fibroblasts in both tissues were not stained with OPCML." (PMID 38622256, 2024).
lymph node metastasis (1 paper, 2021). "In terms of lymph node metastasis, differential expression of NEGR1, NTNG1, XPNPEP2, CD109, OPCML, and PRND had statistical significance in the groups of N0 and N1." (PMID 34737762, 2021).
melanoma (1 paper, 2021). A malignant, usually aggressive tumor composed of atypical, neoplastic melanocytes. "Then, we utilized melanoma cell lines to test the impact of miR-675-3p mimic transfection on the expression of ERG1, IGF1R, and OPCML targets." (PMID 33400243, 2021).
papillary thyroid carcinoma (1 paper, 2025). "In papillary thyroid carcinoma, OPCML expression is higher in the AYA group, potentially due to hypermethylation of the promoter region CpG." (PMID 41374320, 2025).